RIPK3 (receptor interacting serine/threonine kinase 3)
Diseases named in the same sentence as RIPK3 in open-access papers (continued):
Sharing a sentence is not in itself a finding about the gene and the disease.
aneurysm (4 papers, 2020 to 2024). Bulging or ballooning in an area of an artery secondary to arterial wall weakening. "RIPK3 signalling was found to contribute to aneurysm pathogenesis in an elastase‐induced AAA model by inducing VSMC necroptosis and stimulating NF‐κB‐mediated vascular inflammation." (PMID 38873710, 2024). "A study on CaCl2-induced AAA showed that the aneurysm diameter was significantly reduced in RIPK3-knockout mice, as was the smooth muscle cell necroptosis rate." (PMID 35602104, 2022). "A profound protective effect was observed in Ripk3−/− treated with aortic elastase perfusion: 0 of 9 Ripk3−/− mice developed aneurysms (defined as 100% increase in aortic diameter) compared to 8 out of 9 Ripk3+/+ treated mice that did develop aneurysms." (PMID 33142926, 2020). "Elevated levels of RIPK3 and RIPK1 in human abdominal AA (AAA), particularly in α‐SMA+ VSMCs, indicate the involvement of necroptosis in aneurysm pathogenesis." (PMID 38873710, 2024).
asthma (4 papers, 2021 to 2024). "We compared p-MLKL and p-RIPK3 protein levels in human lung tissue sections obtained from 4 healthy controls and 4 asthma patients." (PMID 38987753, 2024). "Using house dust mite (HDM) extract allergens and a stimulation-induced asthma mouse model, the development of asthma pathology was prevented in mice by the inactivation of RIPK1 kinase expression and RIPK3 or MLKL deficiency." (PMID 35967568, 2022). "Taken together, these results showed that the exacerbated lung inflammation in HDM-challenged FADDAEC-KO mice is specifically linked to the loss of FADD in AECs and depends on RIPK3, suggesting that increased necroptosis of FADD-deficient AECs contributes to the worsening of HDM-induced asthma." (PMID 34045680, 2021). "We have demonstrated the upregulation and activation of necroptosis-dependent proteins, RIPK3 and MLKL, in the airway epithelia of asthma patients and animal models." (PMID 38987753, 2024). "Next, using MLKL knockout mice and the RIPK3 inhibitor GSK872, we investigated the effects of TL1A on airway inflammation and airway barrier function through the activation of necroptosis in experimental asthma." (PMID 38987753, 2024). "Serum concentrations of p-MLKL and RIPK3 were significantly elevated in asthma patients compared to healthy controls, but no significant change in the level of HMGB1 was observed (data not shown)." (PMID 38987753, 2024). "One of the limitations of this study is that it is difficult to obtain BALF samples from patients with asthma, and serum levels of RIPK3 and p-MLKL may not be fully representative or conclusive." (PMID 38987753, 2024). "Here, we found that deficiency of PTRF could reduce lung IL-33, ZBP1, phosphor-receptor-interacting protein kinase 3 (p-RIPK3), and phosphor-mixed lineage kinase domain-like (p-MLKL) (necroptosis executioner), and airway inflammation in an HDM-induced asthma mouse model." (PMID 37454215, 2023). "Lack of RIPK1 kinase activity or RIPK3 or MLKL deficiency did not protect mice with intact FADD signaling from HDM-induced airway inflammation, showing that RIPK1-RIPK3-MLKL-mediated necroptosis does not play an important role in HDM-induced asthma in wild type mice." (PMID 34045680, 2021).
autoimmune lymphoproliferative syndrome (4 papers, 2016 to 2025). Autoimmune lymphoproliferative syndrome (ALPS) is a rare, inherited disorder characterized by non-malignant lymphoproliferation, multilineage cytopenias, and a lifelong increased risk of Hodgkin's and non-Hodgkin's lymphoma. "Ripk3−/−Casp8−/− mice develop an autoimmune lymphoproliferative syndrome that precludes their long-term analysis in HFD obesity models." (PMID 39532538, 2025). "Though Mlkl−/−Fadd−/− or Ripk3−/−caspase-8−/− mice are able to fully rescue Ripk1D325A/D325A animals, there were characteristic autoimmune lymphoproliferative syndrome (ALPS) observed in the surviving mice, suggesting the role of activated RIPK1 in mediating inflammation independent of necroptosis." (PMID 36969188, 2023). "Recent studies have shown that the absence of RIPK3 along with either Caspase 8 or FADD caused a lymphoproliferative phenotype in B6 mice, similar to the lymphoproliferation found in Autoimmune Lymphoproliferative Syndrome." (PMID 27669412, 2016).
bladder cancer (4 papers, 2015 to 2024). "In bladder cancer cells, ABT-737 induces cell necrosis when either ZBP1 or RIPK3 are knocked down, which is achieved by upregulating the interaction between ZBP1 and RIPK3." (PMID 36615244, 2022). "The immunohistochemical results of human bladder cancer showed that the expressions of LOX-1 and FATP2 in human bladder tumor tissues were higher than that in paracancerous tissue, and the expression of RIPK3 in tumor tissue was lower than that in paracancerous tissue." (PMID 38461272, 2024). "After analyzing the clinical samples of human bladder cancer, we found that the expression of FATP2 in cancer stages III and IV was higher than that in stages I and II,and the expression of RIPK3 in cancer stages III and IV was lower than that in stages I and II." (PMID 38461272, 2024). "In our study, we found that a circRNA (hsa_circ_0013936) enriched in bladder cancer (BCa)-derived exosomes could regulate the expressions of FATP2 and RIPK3 in PMN-MDSCs." (PMID 38461272, 2024). "After its MCT1- and NHE1-directed entry in oncogenic H-Ras-transformed bladder cancer cells, 3-BrPA activates the PARP and RIPK3/MLKL/Drp1 necrotic axes, presumably together with the RIPK3/MLKL/TRPM7, RIPK3/MLKL/NHE1 and RIPK3/SAPK/JNK necrotic subroutines, in RIPK1-independent manner." (PMID 26198749, 2015). "Here, we found that bladder cancer (BCa)-derived exosomal circRNA_0013936 could enhance the immunosuppressive activity of PMN-MDSCs by regulating the expression of fatty acid transporter protein 2 (FATP2) and receptor-interacting protein kinase 3 (RIPK3)." (PMID 38461272, 2024).
breast tumors (4 papers, 2018 to 2022). "Notably, the loss of RIPK3 expression also associated with the progression to metastasis in human prostate tumors, and higher-grade adrenocortical and breast tumors." (PMID 30157175, 2018). "Previous findings showed that RIPK3 was upregulated in late-stage breast tumors, implying a promising role of necroptosis in tumor progression." (PMID 35590418, 2022). "Another study regarding mouse MMVT-PyMT breast tumor showed that RIPK3 expression was decreased in the early stages, but a significant increase of RIPK3 and MLKL expression was detected in late stage tumors that bear tumor necrosis, suggesting the necroptosis promotes tumor development 17,18." (PMID 32742497, 2020). "Interestingly, while consistent with previous findings, we found that RIPK3 expression is decreased in the early stages of mouse MMVT-PyMT breast tumors, a significant increase of RIPK3 expression was detected in late stage tumors that bear tumor necrosis." (PMID 31922095, 2019).
chronic lymphocytic leukemia (4 papers, 2016 to 2025). "In chronic lymphocytic leukemia cells (CLL), RIPK3 and CYLD were downregulated and lymphoid enhancer-binding factor 1 (LEF1) acts as a transcription repressor for CYLD." (PMID 27429198, 2016). "Similarly, the low levels of RIPK3 and CYLD expression developed chronic lymphocytic leukemia (CLL) cells to resistance from TNF-α/zVAD-induced necroptosis." (PMID 36361505, 2022).
chronic obstructive pulmonary disease (4 papers, 2021 to 2024). A chronic and progressive lung disorder characterized by the loss of elasticity of the bronchial tree and the air sacs, destruction of the air sacs wall, thickening of the bronchial wall, and mucous accumulation in the bronchial tree. "The levels of RIPK3 are remarkably high in the lung epithelial cells of patients with chronic obstructive pulmonary disease (COPD)." (PMID 38684668, 2024). "A recent study reported that phosphorylated RIPK3 and MLKL signaling promotes inflammation, airway remodeling, and emphysema in chronic obstructive pulmonary disease (COPD) in the lung tissue of COPD patients." (PMID 35806033, 2022).
Cirrhosis (4 papers, 2020 to 2025). A chronic disorder of the liver in which liver tissue becomes scarred and is partially replaced by regenerative nodules and fibrotic tissue resulting in loss of liver function. "In humans, Mlkl levels have been shown to be positively correlated with fibrotic markers in liver samples from patients with fibrosis/cirrhosis, and Ripk3 levels are correlated with increased inflammation and fibrosis in patients with MASH." (PMID 39514172, 2024). "We considered using a RIPK3 deletion mouse but the fact that these animals develop variable degrees of liver injury and fibrosis and makes it an unsuitable model of cirrhosis and ACLF." (PMID 34921136, 2021). "In addition to inhibiting RIPK1 and RIPK3, inhibition of the TLR4 pathway by TAK-242 or TLR4 deficiency was found to significantly reduce circulating ammonia levels, which was validated in clinically relevant models of hyperammonemia due to cirrhosis or UCD." (PMID 40053595, 2025). "RIPK3 plasma levels and hepatic expression of RIPK1, RIPK3, and pMLKL were measured in healthy volunteers, stable patients with cirrhosis, and in hospitalized cirrhotic patients with acutely decompensated cirrhosis, with and without ACLF (AD)." (PMID 34921136, 2021). "Serum RIPK3 was undetectable in 94.3 or 92.9% of HCs or non-ACLF patients without cirrhosis, respectively." (PMID 32655398, 2020).
Cognitive impairment (4 papers, 2021 to 2025). Abnormal cognition is characterized by deficits in thinking, reasoning, or remembering. "RIPK3, a key regulator of necroptosis, has been demonstrated to contribute to TBI-induced cognitive impairment, as evidenced by a study showing that RIPK3 knockout significantly improves spatial learning and memory in TBI mice." (PMID 41369366, 2025). "Another study showed that neuron-specific deficiency of RIPK1 or RIPK3 significantly enhances cognitive performance of TBI mice, indicating that RIPK1 or RIPK3 serve as viable therapeutic targets for post-TBI cognitive impairment." (PMID 41369366, 2025). "Interestingly, our data suggested that RIPK3 knockout also ameliorates cognitive dysfunction in SAE mice, indicating that necroptosis is associated with cognitive impairment in SAE mice." (PMID 36694328, 2023). "RIPK3−/−, but not MLKL−/− mice, were protected against postinjury motor and cognitive deficits at 1–4 weeks (RIPK3−/− vs WT: p < 0.05 for group in wire grip, Morris water maze hidden platform trials, p < 0.05 for novel object recognition test, p < 0.01 for rotarod test)." (PMID 34753914, 2021). "For instance, RIPK3, a central mediator of necroptosis in post-TBI cognitive impairment, not only facilitates necroptosis but also promotes apoptosis through caspase-8 and caspase-3 activation." (PMID 41369366, 2025). "However, STING overexpression did not deteriorate cognitive impairment in RIPK3−/− mice with SAE, indicating that STING is upstream involved in necroptosis." (PMID 36694328, 2023). "Moreover, overexpression of STING did not deteriorate cognitive impairment in SAE RIPK3−/− mice." (PMID 36694328, 2023).
Crohn disease (4 papers, 2016 to 2022). A gastrointestinal disorder characterized by chronic inflammation involving all layers of the intestinal wall, noncaseating granulomas affecting the intestinal wall and regional lymph nodes, and transmural fibrosis. "Abnormal RIPK3 expression is increased in Crohn’s disease (CD) and ulcerative colitis (UC) patients." (PMID 33996591, 2021). "However, in Crohn's disease, activation of mitophagy was found to inhibit RIPK3-dependent necroptosis in the intestinal epithelium." (PMID 33854696, 2021). "Furthermore, abnormal levels of RIPK3 have been found in the intestinal epithelium of both adult and pediatric Crohn's disease patients." (PMID 27344176, 2016). "Interestingly, RIPK3 mRNA expression was significantly lower in tumor versus non-neoplastic tissue both in Crohn's disease and ulcerative colitis patient samples." (PMID 27344176, 2016).
emphysema (4 papers, 2022 to 2025). "Immunohistochemical staining analysis showed that the expression levels of RIPK1, RIPK3, and MLKL in alveolar epithelial cells in the CS group were higher than those in the normal control group, indicating that necroptosis was enhanced in the lungs of mice with emphysema." (PMID 36979417, 2023). "Conversely, the absence of RIPK3 or MLKL reduces CS-induced macrophage death, thereby alleviating airway inflammation, remodeling, and the pathological progression of emphysema." (PMID 41369363, 2025).
esophageal cancer (4 papers, 2014 to 2022). A primary or metastatic malignant neoplasm involving the esophagus. "Our data indicate that RIPK3, necrosomes and autocrine production of TNFα contribute to cisplatin sensitivity by initiating necrosis when the apoptotic pathway is blocked in esophageal cancer cells." (PMID 24959694, 2014). "More importantly, we demonstrate that RIPK3 is necessary for cisplatin-induced killing of esophageal cancer cells because inhibition of RIPK1 activity by necrostatin or knockdown of RIPK3 significantly attenuates necrosis and leads to cisplatin resistance." (PMID 24959694, 2014). "Notably, RIPK3 is required for cisplatin-induced programmed necrosis in esophageal cancer cells." (PMID 24959694, 2014). "In contrast, the high expression of TLR3 in KIRC, ACC, MESO, esophageal carcinoma (ESCA), and uterine carcinosarcoma (UCS); FASLG in HNSC, BLCA, and STAD; RIPK3 in COAD; RIPK1 in MESO and KIRP; FAS in ACC; and FADD in THCA was associated with good survival." (PMID 35748782, 2022). "Taken together, our data indicate that RIPK3 and autocrine production of TNFα contribute to cisplatin sensitivity by initiating necrosis when the apoptotic pathway is suppressed or absent in esophageal cancer cells." (PMID 24959694, 2014).
fibrosis (4 papers, 2018 to 2024). the formation of excess fibrous connective tissue in an organ or tissue in a reparative or reactive process. "To explore the relationship between necroptosis and long-term renal outcome after AKI, we compared tubulointerstitial fibrosis with 40-min ischemia in WT, Ripk3−/−, Mlkl−/− and Ripk3−/−Mlkl−/− mice." (PMID 30158627, 2018).
ileitis (4 papers, 2022 to 2024). "However, the co-ablation of caspase-8 and MLKL downstream of RIPK3 or FADD and RIPK3 in IEC fully protected against cell death and prevented ileitis in mice." (PMID 39840043, 2024).
lung adenocarcinoma (4 papers, 2020 to 2026). A carcinoma that arises from the lung and is characterized by the presence of malignant glandular epithelial cells. "Our multi-omics analyses of samples from patients with primary lung adenocarcinoma revealed that necrosome signaling is repressed because of reduced expression of receptor-interacting protein kinase 3 (RIPK3)." (PMID 41564176, 2026). "Mechanistically, we confirmed the tumor-suppressive role of necrosome signaling through the genetic deletion of Ripk3 in two independent, clinically relevant mouse models of lung adenocarcinoma." (PMID 41564176, 2026). "Thus, RIPK3-mediated inflammatory signaling enhances a diverse immune microenvironment and hinders progression in lung adenocarcinoma." (PMID 41564176, 2026).
lymphoma (4 papers, 2015 to 2022). A malignant (clonal) proliferation of B- lymphocytes or T- lymphocytes which involves the lymph nodes, bone marrow and/or extranodal sites. "Immuno-phenotyping revealed that all lymphomas in Eμ-Myc;Ripk3−/− mice were, as expected, of pro/pre-B (B220+sIg−) or B (B220+sIg+) origin, although there was an increased portion of mixed pre-B/B lymphomas compared with the control Eμ-Myc mice." (PMID 32555451, 2020). "Staining with Annexin V and propidium iodide (PI) revealed that both the parental and the Ripk3-deleted Eμ-Myc lymphoma cells showed classical features of apoptosis (Annexin V+PI−) at early time points after treatment with chemotherapeutic drugs." (PMID 32555451, 2020). "Here, we studied the impact of loss of RIPK3 in a mouse model of MYC-driven lymphomagenesis and on the killing of malignant lymphoma cells induced by chemotherapeutics." (PMID 32555451, 2020). "We compared RIPK1 and RIPK3 protein, and mRNA expression in 17 different epithelial cancer and lymphoma cell lines and found that RIPK1 mRNA and protein were ubiquitously detected in all cancer cell lines tested." (PMID 25675296, 2015). "As the Eμ-Myc mice constitute a model of human Burkitt’s lymphoma, it therefore remains possible that RIPK3 and necroptosis may play a role in other types of lymphoma or other malignancies." (PMID 32555451, 2020). "Moreover, the loss of RIPK3 did not alter the sensitivity of Eμ-Myc lymphoma cells to chemotherapeutic drugs." (PMID 32555451, 2020). "Loss of RIPK3 did not affect the response of Eμ-Myc lymphoma cell lines to S63845." (PMID 32555451, 2020). "We found that Ripk3 deficiency did not accelerate lymphoma development in Eμ-Myc transgenic mice." (PMID 32555451, 2020). "Moreover, RIPK3 and necroptosis might play a role in the response of Eμ-Myc lymphomas (and other tumours) to anti-cancer agents in vivo, perhaps by impacting anti-tumour immune responses from the host, and we will make our cell lines available for such investigations." (PMID 32555451, 2020). "In contrast, RIPK3 mRNA and protein expression was limited to 2 out of 10 epithelial cancer cell lines (HT29 and Colo205) and 4 out of 7 lymphoma cell lines (Jurkat, H9, U937, and BJAB)." (PMID 25675296, 2015). "Moreover, the results indicate that RIPK3 and necroptosis do not play major roles in the response of malignant lymphoma cells to a range of anti-cancer agents, at least under tissue culture conditions." (PMID 32555451, 2020). "Collectively, these findings demonstrate that RIPK3, and by extension necroptotic cell death, is not a major suppressor of MYC-driven lymphoma development." (PMID 32555451, 2020).